GJB3 (gap junction protein beta 3)
Diseases named in the same sentence as GJB3 in open-access papers (continued):
Sharing a sentence is not in itself a finding about the gene and the disease.
lung carcinoma (7 papers, 2017 to 2024). "ALS2CR12 and GJB3 have been associated with lung cancer, with GJB3 predictive of survival rates in LUAD patients." (PMID 39092217, 2024). "Then, we ordered targeted GJB3 small interference RNA, and we used specific GJB3-targeting siRNAs to knockdown the level of GJB3 expression in the lung cancer cells (H2030 and DV90)." (PMID 38728250, 2024). "In CCLE database, the GJB3 was also highly expressed in lung cancer cells." (PMID 39135979, 2024). "Of interest, of all the other connexin genes, this database also identified GJB3 (Cx31) to be significantly associated with poor prognosis in lung cancer (p = 4.56 × 10−4) and in LUAD (p = 3.54 × 10−8) but not in LUSC." (PMID 30845770, 2019). "However, the exact mechanisms by which PSMC1, P2RX1, and GJB3 are involved in the progression of lung cancer have not yet been reported in the literature and warrant further exploration." (PMID 36091041, 2022).
pancreatic cancer (5 papers, 2020 to 2023). "In this study, by comparing the gene expression patterns in primary pancreatic cancer patients primary and liver metastasis specimens, we found that Gap Junction Protein Beta 3 (GJB3) significantly increased in Pancreatic ductal adenocarcinoma (PDAC) liver metastasis." (PMID 36341459, 2022). "GJB3, a member of the connexin gene family, was found to be a potential circulating biomarker for metastatic pancreatic cancer and might have a unique effect on cell death." (PMID 34497634, 2021). "GJB3, TMPRRS4, GPRC5A, and TRIM29 were all identified previously, as upregulated in pancreatic cancer tissues." (PMID 37779898, 2023). "A total of 26 genes were found to be significantly associated with poor prognosis, while five of them, including SYT12, GJB5, RHOJ, GJB3 and IFI27, were of particular interest as they have not been previously associated with poor outcomes in pancreatic cancer cases." (PMID 32724299, 2020).
breast carcinoma (4 papers, 2022 to 2025). "While we did not directly assess its impact on circulating FFA levels in our model, we found CL316243 to increase tumorigenesis and note that lipolysis-inducing agents could feed tumorigenesis in MYC-driven breast cancers with low GJB3." (PMID 40835606, 2025). "Accordingly, GJB3 might serve as a cancer-promoting gene in adenocarcinoma and as a tumor suppressor gene in certain cancers, such as thyroid cancer and breast cancer." (PMID 39135979, 2024). "The study also identified 22 unique ion channels in the metastatic state, of which GRIK2, GJB3, KCNB2, KCNA1 and KCNK2 were previously reported in breast cancer metastasis." (PMID 35326596, 2022).
erythrokeratoderma (4 papers, 2015 to 2023). An umbrella term for a group of rare genetic skin disorders characterized by well-demarcated plaques of reddened, dry and thickened skin. "The remaining three patients had Netherton syndrome (one case due to SPINK5 mutations), erythrokeratoderma (one case due to GJB3 mutation), and KLICK (keratosis linearis with ichthyosis congenita and sclerosing keratoderma) syndrome (one case carrying POMP mutation)." (PMID 29618363, 2018). "At the beginning, Netherton syndrome and Erythrokeratoderma variabilis phenotypes were suspected, but no hair shaft abnormalities were found and no mutations in SPINK5 and EKV genes (GJB2, GJB3, GJB4, GJB6 and KDSR) were identified (data not shown)." (PMID 34983512, 2022).
lung adenocarcinoma (3 papers, 2024). A carcinoma that arises from the lung and is characterized by the presence of malignant glandular epithelial cells. "For the first time, our study used multiple databases to uncover the role of GJB3 in cancer and its impact on the immune microenvironment, verified its role in lung adenocarcinoma, and explored its clinical effectiveness in guiding drug treatment." (PMID 38728250, 2024). "Our study investigated the correlation between GJB3 expression and the drug response in multiple lung adenocarcinoma cell lines." (PMID 38728250, 2024). "Given the prominent prognostic role of GJB3 in lung adenocarcinoma, we next explored the possible implications of GJB3 expression levels in response to various medicines to identify new avenues of personalized therapy." (PMID 38728250, 2024). "In summary, the present research demonstrated that GJB3 may play a role in the development of several different types of cancer, especially Lung adenocarcinoma (LUAD), Pancreatic adenocarcinoma (PAAD) and Mesothelioma (MESO)." (PMID 38728250, 2024).
melanoma (3 papers, 2017 to 2019). A malignant, usually aggressive tumor composed of atypical, neoplastic melanocytes. "In GSE8401 arrays, metastatic melanomas from xenograft models showed downregulated GJA1 (Cx43; LogFC = −2.8; p < 0.001), GJB3 (Cx31; LogFC = −1.8; p < 0.001) and GJB5 (Cx31.1; LogFC = −1.1; p < 0.001) gene expression compared to primary melanomas." (PMID 30717194, 2019). "In datasets using GSE3189 arrays, melanomas showed downregulated GJA1 (Cx43; LogFC = −4.1; p < 0.001), GJB3 (Cx31; LogFC = −3.4; p < 0.001), GJB5 (Cx31.1; LogFC = −3.3; p < 0.001) and upregulated GJB1 (Cx32; LogFC = +1.5; p < 0.001) gene expression compared to nevi." (PMID 30717194, 2019). "Interestingly, this TGF-β activity also correlated with expression of an experimentally validated 6-gene “metagene” (VAV2, CORO1A, EPB41L1, CCT4, FRAP1, GJB3) reflecting integrin β1 activity, further supporting a link between integrin activity and TGF-β activity in human melanoma." (PMID 28448494, 2017). "Such five genes (namely, SCNN1A, GJB3, KCNK7, GJB1, KCNN2) are novel potential melanoma markers or molecular targets, never previously related to melanoma." (PMID 30934896, 2019). "Five such genes (namely: SCNN1A, GJB3, KCNK7, GJB1, KCNN2) were identified as potential strong melanoma markers that had never been identified before." (PMID 30934896, 2019).
pancreatic ductal adenocarcinoma (3 papers, 2022 to 2024). An infiltrating adenocarcinoma that arises from the epithelial cells of the pancreas. "Studies have shown that the expression of GJB3 significantly increases in liver metastasis of pancreatic ductal adenocarcinoma." (PMID 37664112, 2023). "However, the GJB3 is up-regulated in pancreatic ductal adenocarcinoma (PDAC) liver metastasis and GJB3 depletion could suppress the hepatic metastasis of PDAC cells." (PMID 39135979, 2024).
thyroid cancer (3 papers, 2019 to 2024). "In metastatic breast cancer of the bone, the patients with high GJB3 expression exhibit better prognosis, and the high GJB3 expression could reduce the migration, proliferation, and invasion ability of thyroid cancer cells." (PMID 39135979, 2024). "However, GJB3 expression was decreased in thyroid cancer samples, and GJB3 overexpression could reduce the proliferation, migration, and invasion of thyroid cancer cells." (PMID 39135979, 2024).
autosomal dominant deafness (2 papers, 2021 to 2023). "The etiology of autosomal dominant deafness, known as DFNA2B, associated with mutations in the GJB3 gene remains unknown." (PMID 37928735, 2023).
autosomal recessive deafness (2 papers, 2009 to 2019). "The aim of this study is to compare the performance of the in silico pathogenicity prediction tools by testing the missense variants in GJB2 (Cx26), GJB6 (Cx30), and GJB3 (Cx31) genes associated with the autosomal recessive deafness 1A." (PMID 31015822, 2019). "The most common form of hereditary nonsyndromic hearing loss is autosomal recessive deafness 1A (DFNB1A, MIM#220290) caused by pathogenic variants in the GJB2, GJB6, and GJB3 genes encoding connexin 26 (Cx26), connexin 30 (Cx30), and connexin 31 (Cx31) proteins, respectively." (PMID 31015822, 2019).
head and neck squamous cell carcinoma (2 papers, 2024 to 2025). A squamous cell carcinoma that arises from any of the following anatomic sites: lip and oral cavity, nasal cavity, paranasal sinuses, pharynx, larynx, and salivary glands. "GJB3 (Cx31) expression was highest in head and neck squamous cell carcinoma (HNSC) and lowest in uveal melanoma (UVM)." (PMID 40227837, 2025).
ichthyosis (2 papers, 2022 to 2023). Disorders of cornification that are characterized by visible scaling and/or hyperkeratosis of most or all of the skin. "Herein, we report a Chinese family with a missense mutation of GJB3 associated with different clinical symptoms covering EKV, ichthyosis and NSHL." (PMID 35677558, 2022).
nonsyndromic deafness (2 papers, 2011 to 2019). An auditory system disease that is associated with permanent hearing loss caused by damage to structures in the inner ear and/or the middle ear, which is not associated with other signs and symptoms. "Mutations of GJB3 cause three different disorders: nonsyndromic deafness, syndromic deafness, and a genodermatosis." (PMID 23554706, 2011). "As for genetic factors of nonsyndromic deafness in China, the average value of variant in GJB2 seems to be the most common (23.37%), followed by SLC26A4 (14.74%), mtDNA 12SrRNA A1555G ( 2.44%), GJB3 (1.97%) and GJB6 (1.33%) genes." (PMID 23554706, 2011).
pancreatic adenocarcinoma (2 papers, 2024 to 2025). "Furthermore, GJB3 knockdown reduced lung cancer cell proliferation and migration, inhibited the PI3K/AKT pathway in lung adenocarcinoma (LUAD), pancreatic adenocarcinoma (PAAD), and mesothelioma (MESO), and altered pathway activity in H2030, PANC1, and H2452 cancer cell lines." (PMID 40227837, 2025).
papillary thyroid cancer (2 papers, 2019 to 2024). "The expression level of Connexin 31 (Cx31, GJB3) was found to be decreased in primary tumors of papillary thyroid cancer." (PMID 30642339, 2019).
sensorineural hearing loss (2 papers, 2011 to 2012). "The GJB gene family (GJB2, GJB3 and GJB6) encoding gene gap junction proteins – connexins – was found to be the main “storage place" of mutations causing non-syndromic sensorineural hearing loss (SNHL)." (PMID 22567152, 2012).
acute myeloid leukemia (1 paper, 2024). Acute myeloid leukemia (AML) is a group of neoplasms arising from precursor cells committed to the myeloid cell-line differentiation. "In contrast, patients with higher GJB3 levels had a longer OS in Breast invasive carcinoma (BRCA), Acute myeloid leukemia (LAML), and THCA." (PMID 38728250, 2024).
Adrenocortical carcinoma (1 paper, 2024). "As revealed by the Cox regression analysis, high GJB3 expression was associated with a shorter OS for LUAD, PAAD, MESO, Skin cutaneous melanoma (SKCM), LIHC, Thymoma (THYM), and Adrenocortical carcinoma (ACC)." (PMID 38728250, 2024).
bladder cancer (1 paper, 2024). "The present study aims to explore the molecular mechanisms by which loss of GJB3 results in aneuploidy and GJB3's possible involvement in bladder cancer." (PMID 38956497, 2024). "In fact, GJB3 expression is significantly reduced during bladder cancer progression in both humans and murine models, with near complete loss of GJB3 expression in highly invasive stages of disease." (PMID 38956497, 2024). "Next, we investigated the possible correlation between GJB3 and bladder cancer progression by comparing GJB3 mRNA levels in balanced cohorts of NMIBC (n = 103) versus MIBC (n = 62) human bladder tumors using cohorts from the CNUH dataset (GSE13507)." (PMID 38956497, 2024). "In line with this idea, we find that expression of GJB3 is downregulated in human and mouse bladder cancer cells lines as well as in bladder cancer tissue samples derived from patients at time of the trans urethral resection of bladder tumor." (PMID 38956497, 2024). "Bladder tumors analyzed from BBN-induced spontaneous bladder cancer murine models similarly confirmed reduced levels of GJB3 in comparison to normal bladder tissue, implicating a role of reduced GJB3 expression in bladder carcinogenesis." (PMID 38956497, 2024). "We observed that GJB3 levels were substantially lower in bladder cancer cells (RT4, UMUC3 and T24) compared to ureter-derived immortalized epithelial cells (HBLAK, Y235T and UROtsa)." (PMID 38956497, 2024). "We find that GJB3 is highly expressed in the ureter and bladder epithelium, but it is downregulated in invasive bladder cancer cell lines and during tumor progression in both human and mouse bladder cancer." (PMID 38956497, 2024). "When considered in aggregate with tissue expression data for GJB3 protein, we demonstrate that GJB3 expression was significantly reduced on bladder cancer cells." (PMID 38956497, 2024). "On the other hand, the disruption of F-actin-GJB3 interactions alters actin dynamics, which have consequences on the migration and invasion capacities of bladder cancer cell lines." (PMID 38956497, 2024). "Downregulation of GJB3 expression leads to aneuploidy and genomic instability in karyotypically stable urothelial cells and experimental modulation of GJB3 levels alters the migration and invasive capacity of bladder cancer cell lines." (PMID 38956497, 2024). "All together, the data indicate a critical role of GJB3 in bladder cancer initiation and progression." (PMID 38956497, 2024). "In order to acquire additional insight into the role of GJB3 in bladder cancer progression, GJB3 expression was knocked down in RT4 cells, which inherently have a low invasive potential and migratory capacity." (PMID 38956497, 2024). "Immunohistochemistry was used to determine GJB3 levels on human and murine bladder cancer tissue sections." (PMID 38956497, 2024). "When considered in aggregate, these data support our hypothesis that altered GJB3 protein function will compromise the genomic stability of urothelial cells and enhance the invasive potential of bladder cancer cells contributing to metastatic progression." (PMID 38956497, 2024). "Consequently, these observations indicate a possible role for GJB3 in the onset and spreading of bladder cancer and demonstrate a molecular link between enhanced aneuploidy and invasive capacity cancer cells during tumor cell dissemination." (PMID 38956497, 2024).
breast invasive carcinoma (1 paper, 2024). "In a recent comprehensive pan-cancer prognosis review, GJB3 survival analysis indicated that breast invasive carcinoma (BRCA) patients with higher GJB3 levels had a longer overall survival time compared to BRCA patients with lower levels of GJB3." (PMID 39594803, 2024).
breast tumor (1 paper, 2025). "We established a previously unappreciated, functional role for GJB3 gap junctions in activating lipolysis in tumor-adjacent adipose tissue and promoting breast tumor growth in vivo." (PMID 40835606, 2025). "In this study, we observe direct transfer of lipolytic cAMP signaling and contributions to TNBC tumorigenesis by GJB3 gap junctions, a potential link between dependance on fatty acid oxidation observed in TNBC2 and the adipose-rich breast tumor niche." (PMID 40835606, 2025).
cervical cancer (1 paper, 2025). A primary or metastatic malignant neoplasm involving the cervix. "We also studied other GJB family proteins whose expression/roles in cervical cancer had not been previously reported, including GJB3 and GJB4." (PMID 40537499, 2025).
epidermal disease (1 paper, 2024). A skin disease that involves the epidermis. "In addition to Cx26, mutations in GJB6, GJB4, GJB3 and GJA1, encoding Cx30, Cx30.3, Cx31 and Cx43, respectively have also been linked to diverse epidermal diseases." (PMID 38827992, 2024).
Glioblastoma multiforme (1 paper, 2024). "The KM analysis also demonstrated that high GJB3 expression was associated with a worse DSS and PFI of patients with Glioblastoma multiforme (GBM), KIRC, LUAD, MESO, and PAAD." (PMID 38728250, 2024).
Huntington disease (1 paper, 2024). Huntington disease (HD) is a rare neurodegenerative disorder of the central nervous system characterized by unwanted choreatic movements, behavioral and psychiatric disturbances and dementia. "GJB3 has been associated with drugs such as SRT1720, which has potential applications in treating conditions related to aging and metabolic diseases, and SELISISTAT, which is being explored for the treatment of Huntington’s disease." (PMID 39092217, 2024).
liver disorder (1 paper, 2024). A disease involving the liver. "The identification of specific drugs targeting HLA-DRB5, GJB3, HSD17B13, and CD244 for various indications, such as cancer, metabolic diseases, and liver disorders, further strengthens their potential as therapeutic targets in LUAD." (PMID 39092217, 2024).
neuropathy (1 paper, 2021). A disorder affecting the nervous system that manifests with pain, tingling, numbness, and/or muscle weakness. "Mutations in GJB3 can also be associated with hereditary deafness with or without neuropathy." (PMID 33807656, 2021).
ovarian carcinoma (1 paper, 2024). A malignant neoplasm originating from the surface ovarian epithelium. "As a potential drug target for the failure of chemotherapy, Connexin 32 internalization by USP14 inhibition modulates cisplatin resistance in ovarian cancer cells; however, little attention has been paid to the role of GJB3 in cancer, especially from a pan-cancer perspective." (PMID 38728250, 2024).
rectum adenocarcinoma (1 paper, 2024). An adenocarcinoma arising from the rectum. "Additionally, based on clinicopathological features, the findings show that high GJB3 expression represents a higher degree of malignancy in COAD, KIRC, Rectum adenocarcinoma (READ), and LUAD." (PMID 38728250, 2024).
triple-negative breast carcinoma (1 paper, 2025). An invasive breast carcinoma which is negative for expression of estrogen receptor (ER), progesterone receptor (PR), and human epidermal growth factor receptor 2 (HER2). "We find that connexin 31 (GJB3) promotes receptor triple negative breast cancer growth and activation of lipolysis in vivo." (PMID 40835606, 2025).
urothelial carcinoma of the bladder (1 paper, 2024). "The aim of the current study was to explore the molecular mechanism by which the loss of GJB3 leads to aneuploidy-induction in urothelial cells and the role of GJB3 downregulation in the development and progression of urothelial carcinoma of the bladder." (PMID 38956497, 2024).
virus infection (1 paper, 2022). "The real time PCR and immunoblots results showed GJB3 expression was reduced about 85% by shGJB3 lenti-virus infection." (PMID 36341459, 2022).